TLR7 (toll like receptor 7)
Diseases named in the same sentence as TLR7 in open-access papers (continued):
Sharing a sentence is not in itself a finding about the gene and the disease.
cancer (continued). "In the late 1990s, synthetic TLR7/8 agonists were touted as an alternative to FDA-approved high-dose exogenous IFN-α; widespread use of the latter in treating cancer was limited by significant toxicity and exorbitant cost." (PMID 34058283, 2021). "In summary, we designed and manufactured a novel cancer nanovaccine named SVMAV that simultaneously loaded antigenic peptides, the TLR7/8 agonist R848 and the small molecule STAT3 inhibitor stattic." (PMID 34452929, 2021). "Imiquimod, the only TLR7-agonist approved by the FDA and the European Medical Agency (EMA), has been successfully used for cancer immunotherapy, in particular in certain cutaneous tumors." (PMID 34573939, 2021). "For example, we have shown that RcR and RcD NANPs function as TLR7 agonists and such agents, including the FDA approved TLR7/8 agonist imiquimod, are being explored for use as antivirals, cancer therapeutics and vaccine adjuvants." (PMID 33091133, 2020). "The role of pDCs in cancer immunity is relevant due to their capability to produce large amounts of I- and III-IFNs, when properly activated through TLR-7 and -9 agonists, linking the innate and adaptive immune responses." (PMID 32731406, 2020). "In this study we focused on TLR7 and TLR8, as ligands for these two receptors are in clinical use or development for cancer therapy." (PMID 32183240, 2020). "In view of the potential application of Vδ2 T cells as effector cells in cell-based cancer immunotherapy, we investigated the modulation of the activation and proliferative Vδ2 expansion by TLR8 and TLR7/8 ligands." (PMID 32183240, 2020). "Activation of other TLRs, such as TLR2, TLR5, TLR7, TLR8 and TLR9, has been reported to enhance proliferation in various cancers including liver, gastric, lung, and breast cancer." (PMID 31480568, 2019). "Therefore, it seems that TLR7 may play different roles depending on the cancer cell status." (PMID 29854832, 2018). "Agonists of TLR7 and TLR8 including imidazoquinolines are currently being used or tested in clinical trials as anti‐viral and anti‐cancer drugs." (PMID 28923824, 2017). "The scientific and clinical interest in TLR7 and TLR8 in cancer biology has originated from the antitumor activities of these molecules in preclinical models." (PMID 29190907, 2017). "Synthetic TLR3, TLR4, TLR7, and TLR9 ligands are being tested in cancer patients as single agent or in combination with cancer vaccines and ligands for other TLRs are in development." (PMID 28003994, 2016). "Stimulation of TLR7/TLR8 overexpressing PANC1 cells resulted in elevated NF-κB and COX-2 expression, increased cancer cell proliferation and reduced chemosensitivity." (PMID 26134824, 2015). "Gene expression of the proliferation marker Ki-67 in R848 treated TLR7+ and TLR8+ PANC1 cancer cells confirmed these proliferative effects." (PMID 26134824, 2015). "Thus, this study links TLR7 signaling to the functional control of effector T cells and Treg cells and identifies Loxoribin as a new therapeutic strategy in cancer treatment, which may offer new opportunities to improve the outcome of cancer immunotherapy." (PMID 25593198, 2015). "Therefore, this study links TLR7 signaling to the functional control of Treg cells and identifies Loxoribin as a new therapeutic strategy in cancer treatment, which may offer new opportunities to improve the outcome of cancer immunotherapy by administration of TLR7 agonist." (PMID 25593198, 2015). "The promoting effect of TLR7 and TLR8 expression on PANC1 cancer cell proliferation was analyzed using MTS proliferation assays." (PMID 26134824, 2015). "Stimulation with R848 for 6 h induced an ~4-fold increase in gene expression levels of NF-κB in TLR7+ and TLR8+ PANC1 cancer cells compared with untreated cells (P<0.0001)." (PMID 26134824, 2015).
cancer (continued). "For both concentrations increased cell viability of TLR7+ and TLR8+ PANC1 cancer cells was demonstrated when compared to empty vector PANC1 cells, pointing to an increased chemoresistance in the cells." (PMID 26134824, 2015). "Seventy-two hours after stimulation with R848 NF-κB expression returned to background levels in both TLR7+ and TLR8+ PANC1 cancer cells." (PMID 26134824, 2015). "Even 72 h post-stimulation COX-2 expression levels remained significantly elevated in stimulated TLR7+ and TLR8+ cancer cells in comparison to untreated cancer cells." (PMID 26134824, 2015). "Stimulation with the TLR7/TLR8 ligand R848 induced a relative increase in proliferation in TLR7+ and TLR8+ in PANC1 cancer cells compared to empty vector treated PANC1 cells (TLR7+, 206% and TLR8, 251% vs. empty vector, 170%; P<0.02 and P<0.0001)." (PMID 26134824, 2015). "Cell morphology of cancer cells and positive staining for CD34 indicated that cells expressing TLR7 and TLR8 were indeed cancer cells." (PMID 26134824, 2015). "Several TLR ligands, including imiquimod (TLR7) and CpG (TLR9), have shown significant promise for the treatment of cancer." (PMID 25231413, 2014). "Notably, HERVH Xp22.2-AS transcription was strongly anti-correlated with TLR7 and TLR8 transcription in cancers where it was expressed." (PMID 40336011, 2025). "Targeting immune system proteins called TLR7 and TLR8 is showing promise in cancer treatment." (PMID 41228373, 2025). "One example of this is R848, a dual TLR7 and TLR8 synthetic agonist previously shown to promote an anti-cancer and anti-bacterial immune response, suggesting that it might also have relevance in wound healing settings as well." (PMID 39078119, 2024). "Hence, TLR7 agonist R837, the first TLR agonist that approved for cancer treatment, is picked out by us to strengthen the co-stimulating signal." (PMID 38594751, 2024). "Functionally, inhibition of TLR7 through IRS‐954 did not lead to reduced mRNA levels neither in cancer cells nor in THP‐1 monocytic control cells." (PMID 36602302, 2023). "We showed that TLR7 expression was positively correlated with the number of neoantigens in KIRP and negatively correlated with BRCA, READ, STAD, and HNSC after counting the number of neoantigens for each cancer type." (PMID 37362864, 2023). "Given this, we hypothesised that TLR1, TLR2, TLR3, TLR7, TLR8, and TLR9 would be involved in a negative regulatory mechanism mediated by TLR8-AS1 that contributes to the maintenance of cancer stem cell features." (PMID 35801728, 2022). "The intracellular TLRs (TLR3, TLR7, TLR8, and TLR9 in human) can detect viral and bacterial nucleic acids, playing an important role in host immune response and potentially in the treatment of cancer." (PMID 36476317, 2022). "MUC-1 and toll-like receptor 7 (TLR-7) peptide in a murine model of BC were tested, and this vaccine induced CTL response and antibody-dependent cellular cytotoxicity (ADCC) and improved humoral immunity against MUC-1 + cancer cells." (PMID 35000604, 2022). "TLR5, TLR7, and TLR8-AS1 were found to be significant in seven cancers each." (PMID 35801728, 2022). "In summary, TLR7/8 agonists have drawn most research attention among other TLR ligands; despite that preclinical data indicate promising prospects, none of the TLR7/8 agonists has gained regulatory approval to treat cancer in human except Imiquimod." (PMID 36479129, 2022). "TLR7 and TLR8 are key members of the Toll-like receptor family, playing crucial roles in the signaling pathways of innate immunity, and thus become attractive therapeutic targets of many diseases including infections and cancer." (PMID 35452465, 2022). "Additionally, TLR6, TLR7, TLR8, TLR9, and TLR10 expression was up- or down-regulated in different cancer species." (PMID 35801728, 2022). "Consequently, the mRNA incorporated in this study can activate Toll-like receptor 7 (TLR7) on DCs to induce the secretion of IFN and desired anti-cancer responses." (PMID 35335310, 2022).
cancer (continued). "The expression of TLR7 and TLR8 in different kinds of cancers has been studied." (PMID 36476317, 2022). "Here, we have concentrated on the function of TLR4, TLR7, and TLR9 in the cancer in this section." (PMID 35801728, 2022). "The significant reduction in apoptotic cells after TLR7 and HERV-V1/V2 gene ablation validates the involvement of these elements in mediating cell death driven by HTCT, and suggests a possible extrapolation of the SaK concept to cancer therapy." (PMID 33658617, 2021). "The sole expression of HERVs is not an adequate stimulus for recognition by TLR7/8, not even overexpression observed in cancer cells refractory to cytostatic therapy." (PMID 33658617, 2021). "Although RIG-I is expressed in most cell types, TLR-3 and TLR-7 expression is restricted to DCs and other antigen-presenting cells that are present in the TME and are believed to play a critical role in the recognition of cancer by the immune system." (PMID 32088771, 2020). "Indeed, combination treatment with a TLR3 (Hiltonol), TLR7 (imiquimod), TLR7/8 (resiquimod), or TLR9 (CpG 7909) agonist has been shown to enhance humoral and cellular responses in a significant proportion of cancer patients." (PMID 29770138, 2018). "Several interventions targeting macrophages have shown promising results in mouse models for cancer, including a histone deacetylase inhibitor, agonistic anti-CD40 antibodies, TGF-β inhibition in combination with toll-like receptor 7 (TLR7) ligation, and attenuated Listeria monocytogenes." (PMID 30450098, 2018). "Although the roles of TLRs have been reported in inflammation and cancer, TLR7 in HCC has not been much explored." (PMID 27588480, 2016). "Notably, stimulation of TLR7 and TLR8 in the present study also resulted in a more robust chemoresistance in PANC1 cancer cells against 5-fluorouracil." (PMID 26134824, 2015). "We examined whether TLR7 and TLR8 stimulation with the agonist R848 further increases proliferation of TLR7+ and TLR8+ PANC1 cancer cells." (PMID 26134824, 2015). "Moreover, TLR7 and TLR8 stimulation in human PANC1 cancer cells led to the release of inflammatory mediators, mainly through the activation of the NF-κB pathway." (PMID 26134824, 2015). "In PBMCs of HBV-infected patients, TLR7 expression and TLR9 mRNA are down-regulated, but TLR9 shows increased protein expression, which may play important roles in cancer cells." (PMID 21078198, 2010). "Similarly, another study evaluated MEDI9197, a TLR7/8 agonist, when administered alone or in combination with durvalumab and/or palliative radiation in subjects with solid tumors, highlighting the exploration of TLR agonists in cancer therapy." (PMID 38732254, 2024). "Additionally, TLR7 has been shown to alter the susceptibility of cancer cells to 30 medicines, with exception of Irofulven, a semi-synthetic analog of the fungal substance illudin S, which has a negative correlation, implying that an increase in TLR7 may result in Irofulven resistance." (PMID 35801728, 2022). "However, side effects from systemic administration of TLR7 agonists limits their use in non-dermatologic cancers." (PMID 33801967, 2021). "Furthermore, we analyzed TLR7 and TLR8 in dissociated cells derived from the same patient tissues together with CD34, a marker for endothelial cells and known to be expressed by cancer cells with neoangiogenetic potential, by FACS and immunohistochemical analysis (cytospins)." (PMID 26134824, 2015). "In addition, the particles could be endowed with a TLR7 agonist that also serves to strengthen antigen presentation and immune recruitment in lymphoid tissue, which could possibly be extended to TLS developing at the primary cancer site." (PMID 37892935, 2023). "A combination of cyclophosphamide with either the TLR7/8 agonist (3M-011) or TLR7 agonists (852A) verified that cyclophosphamide did not negatively interfere with TLR agonists suppressing cancer but may actually potentiate the effect, depending on the dosing schedule." (PMID 35745800, 2022).
cancer (continued). "Given that certain TLR ligands, in particular the TLR7/8 ligand resiquimod (R848), and the TLR9 ligand CpG, can elicit a strong immune response, these ligands may be used as adjuvants during treatment of virus-infected or cancer patients with high numbers of Tregs." (PMID 23593527, 2013). "Unlike imiquimod, 852A (a TLR7 agonist) and VTX-2337 (a TLR8 agonist) can be administered systemically and are being tested in phase I/II clinical trials against various malignant tumors, e.g., ovarian, breast, cervical, endometrial, and head and neck cancers." (PMID 32012718, 2020). "Because of the TLR3-, TLR7-, and TLR9-mediated CD8+ T-cell response in TH1 mode, agonists specific to these TLRs are used for cancer nonvaccines." (PMID 31480568, 2019). "We found that, despite not having representatives of their families, TLR7, BCL2, EZH2, and MDM2 for example, scored highly using the druggability models (74% or higher using the all-drug-target model; and 85% or higher using the cancer-drug-target model)." (PMID 26699810, 2015).
immune diseases (21 papers, 2012 to 2025). "Codon bias in mammalian tlr7 leading to low cytosine-guanine (CG) content was shown to limit tlr7 transcription and this has been proposed to form a regulatory mechanism to prevent over-expression of TLR7 which can lead to auto-immune disease." (PMID 30483270, 2018). "And gender difference in TLR7 response has been reported previously in human immune diseases." (PMID 30736860, 2019). "Surprisingly, however, TLR9 deficiency in the presence of normal TLR7 function reduces only anti double-strain-DNA autoantibody levels, but not other autoantibodies and is associated with a more severe AI disease, suggesting a regulatory role of TLR9 for TLR7-mediated immune disease." (PMID 22826712, 2012). "B. breve CCFM1026 significantly reduced the proportion of neutrophils and increased lymphocytes, the expressions of TLR7, MyD88, TRAF6, and TNF-α to restore the immune disorders." (PMID 33924002, 2021). "Given the function of IMQ as an immune adjuvant that induces a Th1-dominated immune environment and binding with TLR7 to inhibit the inflammatory response, we believe that IMQ can regulate the pathogenesis of the UC immune disorder, thereby potentially playing a role in treatment." (PMID 29049372, 2017). "TLR4, TLR7, and TLR21 expression levels in G1 broilers without cold stimulation training were considerably down-regulated after ACS, indicating that ACS leads to immune dysfunction in broilers." (PMID 36496781, 2022).
infectious disease (15 papers, 2010 to 2025). A disorder directly resulting from the presence and activity of a microbial, viral, or parasitic agent in humans. "The results suggested that SE(Trojan-TLR7/8a) can be used as a potent adjuvant for vaccination against various infectious diseases that are associated with increased morbidity and mortality in aged patients." (PMID 40562869, 2025). "In variant strain infectious bursal disease virus-infected bursa, TLR7 expression was downregulated at 3 and 5 d.p.i. and upregulated at 7 d.p.i.." (PMID 25874762, 2015). "Fourth, because TLRs are expressed in both non-neuronal and neuronal cell types in the CNS and contribute to both infectious and non-infectious disorders, TLR3 and TLR7 are thought to be major mediators of virus-induced signaling pathways during RSV infection." (PMID 29427996, 2018). "Furthermore, the gene expression profiles matched those of several infectious diseases including influenza virus infection, and upstream regulator analysis predicted both TLR7 and TLR9 as positive regulators and BTK as a negative regulator of gene expression." (PMID 33240770, 2020).
bacterial infections (11 papers, 2013 to 2026). "Given the importance of TLR7 and 9 in protection from viral and bacterial infections, long-term therapeutics, directly targeting TLR7 and 9 are expected to be detrimental to the host’s ability to combat such infections." (PMID 23936008, 2013). "However, the immune responses initiated by R848 through the TLR7/8 pathway in response to bacterial infection remain largely unexplored in teleosts." (PMID 33537035, 2020). "Toll-like receptor 7 (TLR7) and TLR8 are endosomal ssRNA sensors that initiate innate immune responses during viral and bacterial infections." (PMID 37462944, 2023). "Given that TLR3 and TLR7 are antiviral receptors (Iqbal, Philbin & Smith, 2005) that are induced in response to viral challenge, it is not surprising that bacterial infection did not enhance their expression." (PMID 30701142, 2019).
kidney disease (10 papers, 2011 to 2025). "Thus, TLR7 deficiency exclusively in B cells is sufficient to ameliorate the exacerbated renal disease observed in MRL/lpr mice globally deficient for TLR9." (PMID 37606042, 2023). "We examined whether TLR7 SNPs were associated with clinical phenotypes such as the presence of anti-Sm antibodies, anti-double-stranded DNA antibodies and renal disorder." (PMID 21396113, 2011). "Our prior data consistently demonstrate that global deletion of Tlr7 resulted in only a modest reduction in renal disease compared with WT controls." (PMID 37606042, 2023). "Our study shows that oral exposure to EE, even at a very low dose, can exacerbate azotemia, increase clinical markers of renal disease, enhance glomerular immune complex deposition, and modulate TLR7/9 cytokine production in female MRL/lpr mice." (PMID 32251357, 2020). "We also evaluated the clinical parameters of kidney disease in mice stimulated in vivo with imiquimod (a TLR7 agonist as a surrogate for viral exposure) and ODN 2395 (a TLR9 agonist, as a surrogate for bacterial exposure)." (PMID 32251357, 2020). "We started topical resiquimod treatment of NZM2410 mice at 10 weeks of age, and assessed protein levels at 15 weeks of age, allowing for observation of possible early onset of renal disease due to TLR7 agonism." (PMID 31998321, 2019). "Several previous studies have demonstrated the role of TLR7 in the development of kidney disease." (PMID 37596656, 2023). "Although increased TLR7 has been implicated in several autoimmune and inflammatory diseases, its role in kidney disease development has not been extensively investigated." (PMID 37596656, 2023). "However, previous studies only found higher BAFF levels in the serum when crossing Sle1 mice with an autoimmune accelerator that overexpresses TLR7, resulting in severe systemic autoimmunity and kidney disease." (PMID 36923413, 2023). "Albuminuria in these 15 weeks old TLR7-stimulated NZM2410 mice were similar to that seen in NZM2410 mice at 18 weeks of age (early stage renal disease, typically 0–100 μg/24 h), so albuminuria is indeed accelerated for age in comparison to vehicle-treated NZM mice." (PMID 31998321, 2019). "Thus, while TLR7 stimulation is accelerating kidney disease in NZM2410 mice, the kidney disease observed, as measured by both histopathology and a functional endpoint, did not result in their death." (PMID 31998321, 2019). "Although TLR-7 or -9 deficiency each diminished the production of specific types of autoantibodies in MRL/lpr mice, only TLR-7 deficiency diminished lymphocyte activation, IgG production, and kidney disease." (PMID 29556239, 2018).